DTL (denticleless E3 ubiquitin protein ligase adapter)
Description:
Substrate-specific adapter of a DCX (DDB1-CUL4-X-box) E3 ubiquitin-protein ligase complex required for cell cycle control, DNA damage response and translesion DNA synthesis. The DCX(DTL) complex, also named CRL4(CDT2) complex, mediates the polyubiquitination and subsequent degradation of CDT1, CDKN1A/p21(CIP1), FBH1, KMT5A and SDE2. CDT1 degradation in response to DNA damage is necessary to ensure proper cell cycle regulation of DNA replication. CDKN1A/p21(CIP1) degradation during S phase or following UV irradiation is essential to control replication licensing. KMT5A degradation is also important for a proper regulation of mechanisms such as TGF-beta signaling, cell cycle progression, DNA repair and cell migration. Most substrates require their interaction with PCNA for their polyubiquitination: substrates interact with PCNA via their PIP-box, and those containing the 'K+4' motif in the PIP box, recruit the DCX(DTL) complex, leading to their degradation. In undamaged proliferating cells, the DCX(DTL) complex also promotes the 'Lys-164' monoubiquitination of PCNA, thereby being involved in PCNA-dependent translesion DNA synthesis. The DDB1-CUL4A-DTL E3 ligase complex regulates the circadian clock function by mediating the ubiquitination and degradation of CRY1.
Synonyms: CDT2; DCAF2; L2DTL; RAMP
Tractability: Antibody: UniProt places it where antibodies can reach, with medium confidence. PROTAC: UniProt records ubiquitination sites on it; ubiquitination databases record sites on it.
Gene: Protein-coding gene on chromosome 1 (212,035,553 to 212,107,400, forward strand). Ensembl gene ENSG00000143476.
Subcellular location: Nucleus; Nucleus membrane; Cytoplasm, cytoskeleton, microtubule organizing center, centrosome; Chromosome
Subcellular location (Human Protein Atlas): Nucleoplasm; Cytosol; Nucleoli
Pathways (Reactome):
DNA Repair: Recognition of DNA damage by PCNA-containing replication complex
Metabolism of proteins: Neddylation
Gene Ontology:
Molecular function: protein binding; ubiquitin-protein transferase activity; protein-macromolecule adaptor activity
Biological process: DNA damage response; mitotic G2 DNA damage checkpoint signaling; positive regulation of G2/M transition of mitotic cell cycle; positive regulation of protein catabolic process; protein monoubiquitination; protein polyubiquitination; regulation of cell cycle; response to UV; translesion synthesis; ubiquitin-dependent protein catabolic process; proteasome-mediated ubiquitin-dependent protein catabolic process; regulation of cell cycle phase transition; regulation of DNA-templated DNA replication initiation; protein ubiquitination
Cellular component: centrosome; Cul4-RING E3 ubiquitin ligase complex; Cul4A-RING E3 ubiquitin ligase complex; Cul4B-RING E3 ubiquitin ligase complex; nucleoplasm; nucleus; chromosome; nuclear membrane
Genetic constraint (gnomAD): Loss-of-function variants: 27 observed, 58.65 expected, observed/expected ratio (o/e) 0.46, 90% interval 0.34 to 0.63. The upper end of that interval is the gene's LOEUF score, 0.63, which puts it in group 2 of 6, group 1 being the genes least tolerant of losing a copy. Missense variants: 580 observed, 730.49 expected, observed/expected ratio (o/e) 0.79, 90% interval 0.74 to 0.85. Synonymous variants: 251 observed, 271.07 expected, observed/expected ratio (o/e) 0.93, 90% interval 0.83 to 1.03.
Homologues: Orthologues: chimpanzee DTL (99% identical), macaque DTL (98% identical), rabbit DTL (95% identical), dog DTL (93% identical), guinea pig DTL (90% identical), pig DTL (90% identical), mouse Dtl (89% identical), rat Dtl (89% identical), tropical clawed frog dtl (54% identical), zebrafish dtl (46% identical), Drosophila melanogaster l(2)dtl (29% identical), Caenorhabditis elegans cdt-2 (22% identical).
Diseases named in the same sentence as DTL in open-access papers:
DTL is named in the same sentence as 67 diseases in open-access papers, as found by Europe PMC text mining. Sharing a sentence is not in itself a finding about the gene and the disease. The quoted sentences say what the papers report.
breast carcinoma (24 papers, 2010 to 2025). "PCLAF and ISG15 overexpression are associated with poor prognosis of breast cancer, and DTL knockdown decreases breast cancer cells’ proliferation and metastasis." (PMID 33662042, 2021). "DTL expression has also been associated with generation of breast cancer in preclinical models, indeed inhibition of this protein reduced cancer growth, through its interaction with Aurora kinase B22." (PMID 29235520, 2017). "Furthermore, we screened three mRNAs (ESR1, ADRA2A, and DTL) associated with breast cancer drug resistance from key genes." (PMID 34490040, 2021). "Studies have shown that DTL expression is up-regulated in breast cancer tissues, but how it plays a role in radiotherapy for breast cancer has not been reported." (PMID 38609375, 2024). "In order to further explore how ubiquitination of RUVBL1 by DTL regulates the radiation resistance of breast cancer cells, we then performed transcriptomic analysis (RNA-seq) on radiation-irradiated breast cancer cells stably overexpressing RUVBL1." (PMID 38609375, 2024). "These breast cancer cells were subsequently irradiated with different radiation doses, and overexpression of DTL significantly increased cell viability and proliferation." (PMID 38609375, 2024). "Subsequently, we confirmed that DTL plays a regulatory role in the radiation resistance of breast cancer cells, and mediates the effect of RUVBL1 on the radiation resistance of breast cancer cells." (PMID 38609375, 2024). "The results indicate that DTL plays a crucial role in the radiation tolerance of breast cancer cells by ubiquitinating RUVBL1 at the K63 site." (PMID 38609375, 2024). "In vitro experiments revealed that DTL overexpression promoted the proliferation, migration and invasion of cervical and breast cancer cell lines, while knockdown of DTL attenuated the growth of cancer cells." (PMID 37038185, 2023). "The potential roles of DTL have been explored in human cancers, for example, ovarian cancer, melanoma, colon cancer, breast cancer, and hepatocellular carcinoma." (PMID 35103094, 2022). "Elevated expression of DTL has been found to be related to a variety of cancers, such as breast cancer, Ewing sarcoma and ovarian cancer." (PMID 35991567, 2022). "The Venn diagram indicated that 2/53 (3.77%) of hub mRNAs (ADRA2A and DTL) were overlapped with breast cancer drug resistance genes." (PMID 34490040, 2021). "It has been reported that DTL plays an essential role in cell proliferation, cell cycle arrest and metastatic potential in hepatocellular carcinoma, breast cancer, gastric cancer and rhabdomyosarcoma." (PMID 32153633, 2020). "Two genes, the ubiquitin-conjugating enzyme E2T (UBE2T) and the denticleless protein homolog (DTL) were overexpressed and linked with detrimental outcome in basal-like and luminal breast cancer patients." (PMID 29235520, 2017). "There are many candidate genes; CENF, KIF14, DTL, NEK2, CKS1B, ASPM and EXO1 each of which are significantly associated with poor clinical outcome in breast cancer patients." (PMID 25312014, 2014). "DTL played an essential role in cell proliferation, cell cycle arrest and metastatic potential in heptacellular carcinoma, breast cancer, gastric cancer and rhabdomysarcoma." (PMID 25186767, 2014). "The subsequent filtering with the combined p-value <0.005 across 6 datasets, yielded 7 candidate genes ASPM, KIF14, NEK2, DTL, CENPF, CKS1B and EXO1 that are significantly associated with poor clinical outcome of the breast cancer patients." (PMID 24147022, 2013). "Hence, targeting CDK1 and DTL presents promising avenues for cancer therapy, particularly in breast cancer, emphasizing the need for further research and clinical trials to establish their efficacy." (PMID 39567714, 2024).
breast carcinoma (continued). "Other dysregulated mRNA that can play important roles in tumor cell behavior as per MammaPrint breast cancer profile were the upregulated DTL and RASSF7 mRNA whose proteins are involved in uncontrolled cell cycle and in microtubule cytoskeleton and spindle formation respectively." (PMID 29203780, 2017). "DTL, ECT2, MTDH, PRC1 and RFC4 have all been previously implicated in breast cancer; SCUBE2 and STK32B deletions have been found to be related to mental deficits in humans; and ZNF533 has been found to be associated with the Hedgehog signaling pathway in Zebrafish." (PMID 20584321, 2010). "Therefore, we speculated that DTL may be involved in the regulation of RUVBL1 on the radiation resistance of breast cancer cells." (PMID 38609375, 2024). "DTL, also known as retinoic acid-regulated nuclear matrix-associated protein (RAMP), or DNA replication factor 2 (CDT2), is reported to be correlated with the cell proliferation, cell cycle arrest and cell invasion in hepatocellular carcinoma, breast cancer and gastric cancer." (PMID 20433742, 2010). "Subsequently, it was discovered that the overexpression of RUVBL1/DTL greatly increased the expression of NHEJ repair pathway molecules, namely K70, K80, DNA-PKcs, 53BP1, LIG4, and XRCC4, within breast cancer cells." (PMID 38609375, 2024). "To further understand the role of RUVBL1 and DTL in the regulation of breast cancer radiation resistance, we knocked down DTL in RUVBL1-overexpressing MDA-MB-231 cells to analyze the resistance of breast cancer to radiation therapy." (PMID 38609375, 2024). "Knockdown of β-catenin in breast cancer cells overexpressing RUVBL1 and DTL significantly reduced the expression level of NHEJ molecules." (PMID 38609375, 2024). "DTL/RAMP, significantly upregulated in breast cancer, exhibits cell-cycle-dependent localization and highest expression at G1/S phases." (PMID 39567714, 2024). "In this study, we elucidated that ubiquitination of RUVBL1 by DTL promotes the formation of RUVBL1/2-β-catenin complex, which in turn promotes the NHEJ repair pathway of breast cancer cells to resist radiation therapy." (PMID 38609375, 2024). "Denticleless E3 ubiquitin protein ligase homolog (DTL), a critical regulator of chromosome segregation, DNA replication, and cell division, is elevated in human gastric and breast cancers and various cell lines derived from these primary tumors." (PMID 38133379, 2023). "In vitro experiments demonstrated that DTL interacts with PDCD4 and ubiquitinates PDCD4 to promote the migration, invasion, and proliferation of breast cancer cells." (PMID 35103094, 2022). "Sub-localizations of DTL and PDCD4 were analyzed in breast cancer cell lines MDA-MB-468 and BT549 using Laser Confocal Microscopy." (PMID 31409387, 2019). "DTL (denticleless E3 ubiquitin protein ligase), also known as CDT2/RAMP/DCAF2/L2DTL, has an oncogenic function in several cancer types, such as breast cancer, hepatocellular carcinoma (HCC), gastric cancer, and Ewing sarcoma." (PMID 31729978, 2019). "We identified the ubiquitin-conjugating enzyme E2T (UBE2T) and the denticleless protein homolog (DTL) as upregulated in basal-like breast tumors and amplified in breast cancer." (PMID 29235520, 2017). "While the breast cancer candidacy of CENPF, KIF14, NEK2, DTL, CKS1B, ASPM and EXO1 genes have been identified earlier, there is only one prominent report indicating the candidacy of EXO1 in breast cancers and remains to be investigated." (PMID 24147022, 2013). "Finally, 6 upregulated DEGs (CST2, DRP2, CLEC5A, SCD, KIAA1211, DTL) and 6 downregulated DEGs (STAC2, BTNL9, CA4, CD300LG, GPIHBP1 and PIGR), were confirmed in a quantitative real time PCR comparison of breast cancer and paracancerous breast tissues from 8 clinical specimens." (PMID 31182966, 2019).
hepatocellular carcinoma (16 papers, 2008 to 2025). A malignant tumor that arises from hepatocytes. "The crucial role of DTL has been previously implicated in genomic stability; however, its prognostic value and its relation with tumor immunity in hepatocellular carcinoma (HCC) remain to be further explored." (PMID 35392073, 2022). "Moreover, the excessive expression of DTL is directly associated with the infiltration of CD3+T-cells in clinical samples obtained from patients with hepatocellular carcinoma, bladder urothelial carcinoma, and stomach adenocarcinoma." (PMID 40723362, 2025). "Even though the oncogenic function of DTL has been investigated in several cancers, its specific role in hepatocellular carcinoma (HCC) still needs further elucidation." (PMID 39384740, 2024). "In line with our observations, KPNA2, DTL, BACE2 and DTYMK were previously found to be associated with tumour stage also in other cancers, including hepatocellular carcinoma or glioma." (PMID 36320118, 2022). "The DTL gene is known for its role in cell proliferation and cell cycle arrest in many cancers such as breast, hepatocellular carcinoma, and gastric cancer." (PMID 34070979, 2021). "Several studies have revealed that DTL has an oncogenic function in several types of cancer, such as hepatocellular carcinoma, breast cancer, and Ewing sarcoma." (PMID 26472028, 2015). "Moreover, targeting DTL expression in human hepatocellular carcinoma inhibits cancer cell growth." (PMID 37689310, 2023).
gastric cancer (14 papers, 2009 to 2025). A primary or metastatic malignant neoplasm involving the stomach. "As a retinoid acid‐regulated nuclear matrix‐associated protein, DTL has been shown to be widely involved in cell proliferation, cell cycle, and cell invasion in breast and gastric cancers." (PMID 37439040, 2023). "Our bioinformatics research showed that DTL expression was increased in almost all GI cancers, which was also confirmed in the clinical pathological samples of our project on colorectal and gastric cancer." (PMID 40723362, 2025). "Lastly, overexpression of DTL has been shown to contribute to lymphatic invasion, tumor depth, recurrence, and poor outcomes in gastric carcinoma." (PMID 31475119, 2019). "Knockdown of DTL in gastric cancer cells induced apoptosis and G2/M arrest whereas overexpression of DTL promoted anchorage-independent growth." (PMID 28336923, 2017). "In contrast, DTL has previously been shown to play an oncogenic role in different cancer types including gastric cancer, ewing sarcoma, melanoma and ovarian cancer." (PMID 28336923, 2017). "DTL overexpression was observed in the KatoIII, NUGC4, HGC27, and MKN28 cells (4/7 lines, 57%), suggesting that the DTL gene is a target for activation in gastric cancer cell lines." (PMID 26472028, 2015). "In this study, we show that DTL is frequently overexpressed in gastric cancer cell lines and primary gastric cancer tissues." (PMID 26472028, 2015). "Western blotting analysis was performed using a DTL-specific antibody to determine DTL protein expression in the gastric cancer cell lines KatoIII, NUGC4, MKN7, HGC27, MKN28, MKN45, and MKN74." (PMID 26472028, 2015). "We demonstrated that DTL was overexpressed in 48% (29/60) of primary gastric cancer tissues and 57% (4/7) of gastric cancer cell lines and that this overexpression was a poor prognosticator independent of other prognostic factors." (PMID 26472028, 2015). "Other integrated analyses have identified EXO 1, DTL, KIF 14, and TRIP13 as significant genes that could serve as potential diagnostic biomarkers related to gastric cancer." (PMID 40445003, 2025). "Overexpression of DTL is related to the poor outcome in gastric carcinoma, breast and lung cancers." (PMID 31788359, 2019). "In addition, downregulation of DTL expression suppressed cell proliferation, migration, and invasion in gastric cancer cell lines." (PMID 26472028, 2015). "In this study, we tested whether DTL acts as a cancer-promoting gene through its activation/overexpression in gastric cancer (GC)." (PMID 26472028, 2015). "Our results provide evidence that DTL could be a promising clinical biomarker for determining malignant properties and a target for molecular therapy in patients with gastric cancer." (PMID 26472028, 2015). "Because DTL protein was overexpressed in some gastric cancer cell lines, it was hypothesized that DTL was also highly expressed in gastric cancer tissues, playing a role in carcinogenesis and malignant outcome." (PMID 26472028, 2015). "In this study, we hypothesized that the overexpression/activation of DTL may promote tumor cell proliferation and/or survival in gastric cancer cells." (PMID 26472028, 2015). "Specific immunostaining of the DTL protein in primary samples was confirmed using gastric cancer cell lines as positive (NUGC4) or negative controls (MKN45)." (PMID 26472028, 2015).
gastric cancer (continued). "DTL was recently reported to have an oncogenic role in gastric carcinogenesis as established by in vitro analyses, and significantly overexpressed in gastric cancer tissues than their adjacent non-cancerous tissues." (PMID 26472028, 2015).
cervical cancer (10 papers, 2016 to 2025). A primary or metastatic malignant neoplasm involving the cervix. "Denticleless E3 ubiquitin protein ligase homolog (DTL) promotes cervical cancer cell EMT through the Rac1-related signaling pathway." (PMID 37049739, 2023). "DTL expression is also elevated in multiple myeloma, non-small cell lung cancer, ovarian cancer, head and neck squamous cell carcinoma, and cervical cancer." (PMID 38133379, 2023). "In this study, we report that a micro-RNA, miR-34a by suppressing HPV E6 protein, destabilizes Cdt2/DTL protein level in HPV infected cervical cancer cell lines." (PMID 35840896, 2022). "In the current study, we found that DTL overexpression promoted the migration and invasion of cervical cancer cells, leading to adverse prognosis of patients with cervical adenocarcinoma." (PMID 34635635, 2021). "In particular, DTL overexpression encourages the invasion and migration of cervical cancer cells." (PMID 34635635, 2021). "Of TLS genes, increased expression of SPRTN, DTL, POLD1, PCNA, and VCP occurred most often in cervical cancers." (PMID 36266721, 2022). "In the present paper we identified six putative biomarkers (AURKA, DTL, HMGB3, KIF2C, NEK2, and RFC4) which should be further tested to separate indolent HPV related cervical infections from progressive CIN III lesions and for early diagnosis of cervical cancer." (PMID 26701206, 2016). "To confirm the effect of miR-17 ~ 92 cluster on Cdt2/DTL transcript in cervical cancer cells, we transfected the miR-17 ~ 92 expressing plasmid in HPV positive cervical cancer cell; SiHa, HPV negative cervical cancer cell; C33A and non-cancerous cell line; HEK293T." (PMID 37707654, 2023).